USP17L1 (ubiquitin specific peptidase 17 like family member 1)
Description:
Deubiquitinating enzyme that removes conjugated ubiquitin from specific proteins to regulate different cellular processes that may include cell proliferation, progression through the cell cycle, apoptosis, cell migration, and the cellular response to viral infection.
Synonyms: USP17L1P
Tractability: No criterion of Open Targets' tractability assessment is met for any kind of drug.
Gene: Protein-coding gene on chromosome 8 (7,332,387 to 7,333,979, forward strand). Ensembl gene ENSG00000230549.
Subcellular location: Nucleus; Endoplasmic reticulum
Pathways (Reactome):
Metabolism of proteins: Ub-specific processing proteases
Gene Ontology:
Molecular function: cysteine-type deubiquitinase activity
Biological process: regulation of apoptotic process; protein deubiquitination
Cellular component: endoplasmic reticulum; nucleus
Genetic constraint (gnomAD): Loss-of-function variants: 20 observed, 11.82 expected, observed/expected ratio (o/e) 1.69, 90% interval 1.15 to 1.95. The synonymous counts are far from expectation, so gnomAD's model fits this gene poorly and the ratio says little. Missense variants: 254 observed, 162.3 expected, observed/expected ratio (o/e) 1.57, 90% interval 1.41 to 1.74. Synonymous variants: 89 observed, 60.78 expected, observed/expected ratio (o/e) 1.46, 90% interval 1.23 to 1.75.
Homologues: Paralogues in human: USP17L3 (99% identical), USP17L4 (97% identical), USP17L2 (96% identical), USP17L8 (95% identical), USP17L18 (94% identical), USP17L11 (94% identical), USP17L17 (94% identical), USP17L20 (94% identical), USP17L22 (94% identical), USP17L19 (94% identical), USP17L24 (94% identical), USP17L25 (94% identical), and 59 more.